AFP (alpha fetoprotein)
Diseases named in the same sentence as AFP in open-access papers (continued):
Sharing a sentence is not in itself a finding about the gene and the disease.
fatty liver disease (20 papers, 2012 to 2025). A reversible condition wherein large vacuoles of triglyceride fat accumulate in liver cells via the process of steatosis. "A few studies have suggested a positive association between AFP level and hepatic steatosis or metabolic syndrome." (PMID 35862314, 2022). "In conclusion, we present a case in which hepatic steatosis is the only possible cause of the persistently elevated AFP level after curative resection of HCC." (PMID 22559879, 2012). "There is a correlation between having high AFP levels and insulin resistance, which may be caused by hepatic steatosis." (PMID 37655263, 2023). "A possible mechanism for the association between metabolic syndrome and elevated AFP may be due to insulin resistance and fatty liver disease." (PMID 36684957, 2022). "The main potential mechanisms accounting for the association between MS and high AFP levels may be IR and hepatic steatosis." (PMID 27121855, 2016). "The presence of hepatic inflammation, steatosis, and/or fibrosis may be the underlying cause of increased serum AFP levels in FLD patients with severe fatty liver." (PMID 27121855, 2016). "At the same time, the patients with NICCD can also be accompanied by elevated liver enzymes, hyperbilirubinemia, significantly elevated alpha-fetoprotein, hypoalbuminemia, prolonged prothrombin time and fatty liver." (PMID 37063661, 2023). "Thus, we aimed to investigate the clinical characteristics of patients with an elevated AFP level >7 ng/mL and its relationship with body composition in terms of hepatic steatosis, visceral adiposity, myosteatosis, and muscle mass." (PMID 35862314, 2022). "Elevated AFP levels in asymptomatic individuals may play a role in expressing a protective phenotype against hepatic steatosis, myosteatosis, and sarcopenia." (PMID 35862314, 2022). "NAFLD/NASH-associated HCC is becoming increasingly common, particularly in western countries; however, the elevation of AFP levels associated with NAFLD/NASH or Fatty liver disease is believed to be not as significant as their viral counterparts." (PMID 36013482, 2022). "In conclusion, asymptomatic adults with elevated AFP levels may play a role in expressing a protective phenotype against hepatic steatosis, myosteatosis, and sarcopenia." (PMID 35862314, 2022). "The results of Xu and other researchers suggested that there was a significant association of serum AFP levels and fatty liver disease but as a cofactor, not as an independent factor." (PMID 30366460, 2018). "AFP levels become increasingly elevated as the grade of liver steatosis increases, which suggests that AFP level monitoring might help clinicians to treat NAFLD." (PMID 27121855, 2016). "Recently, studies have reported that participants with fatty liver disease have higher serum alpha-fetoprotein levels than those without." (PMID 27121855, 2016). "However, most patients with elevated AFP levels did not have fatty liver disease, to our impression." (PMID 35862314, 2022). "Furthermore, in a cross-sectional study that enrolled 9800 subjects, 2601 of which diagnosed with fatty liver disease (FLD), subjects with FLD had higher serum AFP levels than those without, which is concordant with our results." (PMID 32341704, 2020).
metabolic syndrome (20 papers, 2015 to 2025). A cluster of metabolic risk factors for CARDIOVASCULAR DISEASES and TYPE 2 DIABETES MELLITUS. "Logistic regression analysis was used to examine associations between alpha-fetoprotein and metabolic syndrome." (PMID 27121855, 2016). "We investigated the association between alpha-fetoprotein levels and the prevalence of metabolic syndrome in a Chinese asymptomatic population." (PMID 27121855, 2016). "Elevated AFP levels have been associated with metabolic syndrome, and stromal cells differentiating into adipocytes suggesting that mature BMAds may also produce this protein and it may be upregulated upon exposure to myeloma cells." (PMID 36713534, 2022). "The association between the components of metabolic syndrome (central obesity, elevated blood pressure, elevated triglycerides, reduced high-density lipoprotein cholesterol, and elevated fasting plasma glucose) and alpha-fetoprotein levels was evaluated." (PMID 27121855, 2016). "Logistic regression analyses showed an association between alpha-fetoprotein levels and increased risk for metabolic syndrome, the presence of reduced high-density lipoprotein cholesterol, and elevated fasting plasma glucose, but not with obesity, elevated blood pressure, or triglycerides." (PMID 27121855, 2016). "Impaired glucose metabolism and dyslipidemia may play a major role in the association between AFP and MS." (PMID 27121855, 2016). "Therefore, the association between AFP levels and fatty liver or metabolic syndrome is unclear." (PMID 35862314, 2022). "The factors associated with a high risk of HCC were decompensated cirrhosis, metabolic syndrome, failure to obtain SVR, and a baseline AFP level of ≥ 10 ng/dL." (PMID 36117166, 2022). "The lack of evaluation of HBV genotype, the evolution of transaminases, alpha-fetoprotein levels, smoking, and components of the metabolic syndrome throughout the follow-up period is also a limitation of the study." (PMID 36146774, 2022). "Variants of the albumin genes family, including the fetal counterpart of serum albumin (AFP) and afamin/alpha-albumin (AFM) genes, are associated with the development of the metabolic syndrome in adult humans." (PMID 32071365, 2020). "Another possible explanation for the relationship between AFP and incident DM may be related to metabolic syndrome, which is related to the development of DM, cardiovascular disease, and NAFLD." (PMID 36684957, 2022). "Besides pneumonia, we observed an NICCD-like phenotype with the presence of liver dysfunction, dyslipidemia, aminoacidemia, organic academia, and extremely high levels of alpha-fetoprotein (AFP)." (PMID 31620407, 2019). "Participants with metabolic syndrome had significantly higher (p < 0.001) alpha-fetoprotein levels than those without, though all alpha-fetoprotein levels were within the reference interval." (PMID 27121855, 2016).
Obesity (19 papers, 2016 to 2025). Accumulation of substantial excess body fat. "Obesity could decrease the diagnostic performance of ultrasound, which in turn, reduce the cost-effectiveness of ultrasound ± AFP, but the strategies remained cost-effective." (PMID 37076870, 2023). "Future studies could investigate the diagnostic performance of ultrasound + AFP surveillance on people with obesity so that more robust data could be inputted to our model." (PMID 37076870, 2023). "Other pre-transplantation risk factors include serum biomarkers, such as alpha-fetoprotein (AFP) levels and the neutrophil to lymphocyte ratio (NLR), obesity, bridging therapy or time to transplantation." (PMID 37685524, 2023). "Biannual abdominal ultrasound (USG), with or without alpha-fetoprotein (AFP) testing, remains the standard method, but its sensitivity is compromised by operator dependency and patient-related factors such as obesity and bowel gas." (PMID 40723271, 2025). "When the quality of ultrasound is suboptimal for HCC screening (e.g., due to obesity), future surveillance should be performed using CT or MRI, with or without determining the AFP level, every 6 months." (PMID 36831565, 2023). "However, due to the lack of data for sensitivity of ultrasound + AFP on people with obesity/central adiposity, the early detection rate of this strategy was derived from data on ultrasound surveillance for people with obesity." (PMID 37076870, 2023).
ovarian tumors (19 papers, 2012 to 2025). "AFP is the most useful diagnostic biomarker of ovarian tumors in young females." (PMID 23826706, 2013). "AFP is highly specific for YSTs among germ cell tumors and is rarely positive in other ovarian tumors, such as clear cell carcinoma or endometrioid carcinoma." (PMID 41373846, 2025). "Nearly all ovarian YSTs show markedly elevated serum AFP levels, while it is rarely positive in other ovarian tumors." (PMID 41373846, 2025). "Clinicians should be alert to the possibility of HCO in postmenopausal women presenting with abnormal vaginal bleeding and elevated AFP levels to avoid misdiagnosis as more common ovarian tumors or metastatic cancers." (PMID 40919162, 2025). "In summary, when differentiating YSTs from other benign and malignant ovarian tumors based on ultrasound images is difficult, the patient’s age of onset, clinical manifestations and serum AFP can be used as important references for improving diagnosis." (PMID 38966065, 2024). "Useful markers for the investigation of ovarian neoplasms in children and adolescents include alpha-fetoprotein (AFP), lactate dehydrogenase (LDH), beta subunit of human chorionic gonadotropin (β-hCG), cancer antigen 125 (CA-125) and inhibin." (PMID 37508611, 2023). "In general, ovarian tumors were much larger in size and eventually showed expression of tumor markers AFP or ß-HCG." (PMID 35937851, 2022). "In general, ovarian tumors were much larger in size than ovarian cysts or twisted ovaries and eventually showed tumor marker expression of AFP or ß-HCG." (PMID 35937851, 2022). "Laboratory examinations should include tumor markers of ovarian tumors, namely, AFP, ß-HCG and Ca-125." (PMID 35937851, 2022). "In this work, we report a nanosized GO-functionalized fluorescence microfluidic biosensor for the simultaneous detection and analysis of CA125, HE4, CEA and AFP to potentially diagnose ovarian tumors/cancers." (PMID 36557345, 2022). "Unfortunately, there is still a lack of studies on the simultaneous detection of CA125, HE4, CEA and AFP in serum for the evaluation of ovarian tumors/cancers." (PMID 36557345, 2022). "It was suggested she have ovarian tumor markers—inhibin A, inhibin B, hCG, AFP, and LDH, but these were declined." (PMID 25737742, 2015). "In addition, to the best of our knowledge, this is the first study to simultaneously detect CA125, HE4, CEA and AFP for ovarian tumor/cancer diagnosis." (PMID 36557345, 2022). "AFP is the most useful biomarker for ovarian tumors in young females." (PMID 23826706, 2013). "Multiple tumor markers, such as AFP (alpha-fetoprotein), CEA (carcinoembryonic antigen), HCG (human chorionic gonadotropin), and CA125, have been used for diagnosing ovarian neoplasms." (PMID 30533300, 2018). "Markers such as CA19-9, HE4, AFP, and LDH are sometimes measured in ovarian cancer workups, but they are not specific for choriocarcinoma and are mainly used to help differentiate between ovarian tumor subtypes." (PMID 41373846, 2025). "Tumour markers like AFP, CEA, LDH, CA-125 and CA19-9 are used for the diagnosis of ovarian tumours." (PMID 38289795, 2023). "The current results indicate that CA125 and HE4 are strong indicators, AFP may be helpful, and CEA is a weak biomarker for ovarian tumor/cancer diagnosis, and more samples need to be tested to further validate the results in the future." (PMID 36557345, 2022). "Unlike AFP for hepatic cell carcinoma or CA125 for ovarian tumors, the relationship between TMs and the prognosis of the GC was unclear." (PMID 34246249, 2021). "Serum levels of CEA, Ca 19-9, AFP, β-HCG were within normal levels in patients with ovarian BL, and may be useful in the differential diagnosis of ovarian tumours as they are specific for other neoplasms." (PMID 28770352, 2017). "A 2nd differential diagnosis of primary HCO is the HYST which is another ovarian tumor with hepatoid differentiation and AFP production but it is negative for hepatocyte paraffin-1." (PMID 26213594, 2015).
alcohol abuse (18 papers, 2010 to 2025). The use of alcoholic beverages to excess, either on individual occasions ("binge drinking") or as a regular practice. "Univariate analysis revealed that multinodular HCC, lesion diameter, Child –Pugh classification, alcohol abuse, liver function tests, AFP prior TACE and RECIST and EASL classification were predictive prognostic factors of survival (data not shown)." (PMID 24198841, 2013). "Multivariate analysis showed lesion diameter, Child-Pugh classification, alcohol abuse, tumor response and AFP prior TACE as independent prognostic factors of survival." (PMID 24198841, 2013). "Alcohol abuse, tumor burden, response rate criteria, Child-Pugh classification and AFP prior to the session were identified as independent predictors of survival." (PMID 24198841, 2013). "After multivariate analysis of alcohol abuse, lesion diameter, Child–Pugh classification, AFP level prior to the session and EASL classification were identified as independent prognostic factors of survival." (PMID 24198841, 2013). "Alcohol abuse, tumor burden, response criteria, Child-Pugh and AFP prior to the session were identified as independent predictors of survival whereas, adherence to surveillance programs resulted in significantly better survival in these patients." (PMID 24198841, 2013). "Rather, the presence or absence of progesterone receptor (PR), ER, and AR in HCC and their titers did not have any correlation with alcohol abuse, serum alpha-fetoprotein (AFP) levels, hepatitis B virus markers, or histopathologic types of the tumor." (PMID 23484104, 2013). "Cirrhotic patients had higher prevalence of men, alcohol abuse, and positive hepatitis B surface antigen (HBsAg), higher serum alanine aminotransferase (ALT) and aspartate aminotransferase (AST) levels, higher prevalence of abnormal serum AFP level, and smaller tumors than non-cirrhotic patients." (PMID 28183290, 2017).
Hypoalbuminemia (17 papers, 2005 to 2025). The concentration of albumin in the blood circulation is below the lower limit of normal. "In addition, hypoalbuminemia, hypercholesterolemia and increased serum creatine kinase (CK) were reported in association with increased AFP." (PMID 33801069, 2021). "All are associated with early disease onset and elevated alpha-fetoprotein, while AOA1, AOA2, and AOA4 are further associated with elevated cholesterol and hypoalbuminemia." (PMID 38161589, 2023). "Laboratory findings include hypoalbuminemia and hypercholesterolemia, while alpha-fetoprotein (AFP) value is usually relatively increased, although less than what was reported in AOA2 patients." (PMID 33733696, 2021). "Elevation of AFP is present in 99% of cases and is stable over the course of disease, but it usually do not correlate with disease severity; elevated CK, mild hypoalbuminemia, or hypercholesterolemia can also be present in AOA2 patients." (PMID 33801069, 2021). "Only patient CMT1190 presents hypoalbuminemia, hypercholesterolemia, and elevated IgE with normal alpha-fetoprotein as described in other patients." (PMID 30039206, 2018). "In contrast, by using multivariate analysis, it was found that only BMI < 25, hypoalbuminemia, higher serum AFP level, greater TNM stage grading and poorer differentiation were potential risk contributors for HCC prognosis after surgical treatment." (PMID 27027345, 2016). "The effect of hypoalbuminemia is most pronounced in patients receiving first cycle MWA and remains an indicator of progression risk in optimal bridge to LT candidates with well-preserved liver function, limited HCC burden, and low AFP levels." (PMID 35406456, 2022). "However, according to another study hypoalbuminemia and hypercholesterolemia with normal AFP are the hallmarks of AOA1." (PMID 33801069, 2021).
liver dysfunction (17 papers, 2012 to 2025). "The most consistently demonstrated risk factors for poor OS included liver dysfunction, high AFP level and low PLT count." (PMID 40094011, 2025). "Liver dysfunction typically causes an increase in AFP levels; however, in extreme cases, such as severe liver failure, the synthesis and release of AFP may decrease." (PMID 40519787, 2025). "Laboratory tests showed significantly elevated alpha-fetoprotein (AFP) levels (1147 ng/mL) and mild liver dysfunction (Child-Pugh A/B)." (PMID 41306964, 2025). "Diagnosis is based on a high index of clinical suspicion in patients with liver dysfunction (often with elevated transaminases and highly elevated alpha‐feto protein (AFP)), coagulopathy and renal Fanconi‐like syndrome." (PMID 38974614, 2024). "Liver dysfunction (Child-Pugh B/C), the AFP levels at diagnosis, and the tumor types were similar between men and women." (PMID 39452505, 2024). "We detected a significant increase in Alpha-fetoprotein in hepatopathy compared to a healthy cohort." (PMID 36379988, 2022). "UV analyses determined several significant factors contributing to survival: ECOG PS, serum albumin, AFP levels, switching to sorafenib, advanced stage BCLC C, liver dysfunction (CTP C), tumor progression, and disease progression." (PMID 39609726, 2024). "Liver ultrasonography and AFP monitoring should be considered for the MAS patients, especially those with neonatal cholestasis or liver dysfunction, during long-term follow-ups." (PMID 37886236, 2023).
melanoma (17 papers, 2012 to 2025). A malignant, usually aggressive tumor composed of atypical, neoplastic melanocytes. "Among the top 20 upregulated genes were the alpha fetoprotein (AFP) gene, several genes of the melanoma antigen (MAGE) protein family, and other melanoma-associated genes (MAGE-A4, -10, -12, -B-2; DSCR8, PRAME)." (PMID 37592303, 2023). "Cancer targets for these clinical stage–engineered TCR T cells include: preferentially expressed antigen in melanoma (PRAME), New York esophageal squamous cell carcinoma 1 (NY-ESO), melanoma-associated antigen (MAGE) A4, MAGE A3/A6, MAGE A10 and alpha-fetoprotein (AFP)." (PMID 31544847, 2019). "In addition, numerous CSF tumor markers have been explored to aid in LM diagnosis, including CEA, PSA, CA15-3, CA125, CA199, AFP, NSE, Cyfra 21-1, MART-1, and MAGE-3 in melanoma, however their roles in clinical practice are limited." (PMID 38304432, 2024). "Although no detectable levels of AFP mRNA in the human melanoma cell line MDA-MB-453, this cell line was at least to a certain extent susceptible to hCMV/AFP mediated transfection." (PMID 23734827, 2013). "Both cell types showed negative staining for glial fibrillary acidic protein (GFAP), neuron specific enolase (NSE), HMB45, melanoma-pan, cytokeratin (CK), epithelial membrane antigen (EMA), alpha-fetoprotein (AFP), CD30, human chorion gonadotropin (HCG), SM-action, CD68, CD163, and CD34." (PMID 22515616, 2012).